TACR3 (tachykinin receptor 3)
Diseases named in the same sentence as TACR3 in open-access papers (continued):
Sharing a sentence is not in itself a finding about the gene and the disease.
hypogonadism (6 papers, 2013 to 2024). A disorder characterized by decreased function of the gonads. "The control of serum testosterone levels by TACR3 is consistent with its known role in hypogonadism, whereas the discovery that sex hormones influence TACR3 expression in the hippocampus was a more unexpected finding." (PMID 38135756, 2024). "Loss-of-function mutations in the tachykinin 3 (TAC3) gene, which encodes the stimulatory neuromodulator NKB, and tachykinin receptor 3 (TACR3), which encodes the NKB receptor, are associated with the development of hypogonadism and delayed puberty." (PMID 35328752, 2022). "In addition, the involvement of TACR3 in human reproductive systems such as normal hypogonadism is evident." (PMID 34568491, 2021). "Another important aspect is the possible reversal of TACR3 and TAC3 mutation-related hypogonadism." (PMID 32508745, 2020).
Parkinson disease (4 papers, 2015 to 2023). A progressive degenerative disorder of the central nervous system characterized by loss of dopamine producing neurons in the substantia nigra and the presence of Lewy bodies in the substantia nigra and locus coeruleus. "As neurokinin B, which is the endogenous ligand of TACR3, is well known to be involved in the pathogenesis of Parkinson’s disease, genetic polymorphism of TACR3 in rosacea could be one possible explanation for this association." (PMID 33182618, 2020). "It has been reported that neurokinin B (endogenous ligand of TACR3) is involved in the pathogenesis of Parkinson's disease." (PMID 34568491, 2021). "Neurokinin B (endogenous ligand of TACR3) is involved in pathogenesis of Parkinson's disease by interacting with brain dopaminergic transmission." (PMID 27347521, 2015). "Neurokinin B, involved in the pathogenesis of Parkinson's disease, frequently coexisting with subsequent onset of rosacea, is an endogenous ligand of the tachykinin receptor 3 (TACR3)." (PMID 27347521, 2015).
endometrial carcinoma (3 papers, 2018 to 2022). A malignant tumor arising from the epithelium that lines the cavity of the uterine body. "The heatmap of neuroactive ligand-receptor interaction which closely related with endometrial carcinoma showed hypermethylation of associated genes, including TACR3, in tumor tissues and opposite result in normal tissues." (PMID 30485833, 2018). "It regulates the axis LOC134466/hsa-miR-196a-5p/TAC1, which activates neuroactive ligand-receptor interactions by activating TACR3 in endometrial cancer (EC)." (PMID 36090902, 2022). "TACR3 was found to be highly elevated in endometrial carcinoma." (PMID 36105089, 2022).
oral squamous cell carcinoma (3 papers, 2016 to 2025). "Tachykinin 3 (TAC3) has been shown to affect gingival oral squamous cell carcinoma cells possibly through tachykinin receptor 3 (TACR3) in bone matrix." (PMID 39790460, 2025). "In oral squamous cell carcinoma invaded bone destructed site, SHH from tumor cells might upregulate the tachykinin receptor 3 expression in the preosteoclasts and consequently stimulate osteoclasts differentiation indirect manner." (PMID 27007126, 2016).
rosacea (3 papers, 2015 to 2020). A chronic erythematous skin disorder that affects the face. "In turn, a genetic predisposition to carrying the rs3733631 polymorphic variant in the tachykinin receptor gene TACR3 was also observed in patients with rosacea; notably, this is near the TLR2 gene locus at 4q25." (PMID 27649161, 2016). "Possible involvement of the TACR3 gene in rosacea would most probably be associated with either upregulation or downregulation of this gene." (PMID 27347521, 2015). "It is therefore reasonable to suppose that the polymorphism in TACR3 might be involved in the development of rosacea by enhancing the expression of TLR2." (PMID 27649161, 2016).
breast carcinoma (2 papers, 2020 to 2021). "Likewise, further research of other genetic polymorphisms such as oestrogen receptor and tachykinin receptor 3 loci should also be considered, which might reveal association of hot flashes with tamoxifen administration in breast cancer patients." (PMID 34006247, 2021).
congenital hypogonadotropic hypogonadism (2 papers, 2011 to 2020). Congenital hypogonadotropic hypogonadism (CHH) is a rare disorder of sexual maturation characterized by gonadotropin (Gn) deficiency with low sex steroid levels associated with low levels of follicle stimulating hormone (FSH) and luteinizing hormone (LH). "The authors present a new association of two heterozygous TACR3 mutations (p.Arg230His and p.Trp275*) responsible for a clinical trait of normosmic congenital hypogonadotropic hypogonadism in a family." (PMID 33363893, 2020). "TAC3/TACR3 mutations have been reported in normosmic congenital hypogonadotropic hypogonadism (nCHH) (OMIM #146110)." (PMID 22031817, 2011).
cryptorchidism (2 papers, 2017 to 2020). The failure of one or both testes of a male fetus to descend from the abdomen into the scrotum during the late part of pregnancy. "The frequent presence of a micropenis and cryptorchidism in mutant TACR3 male patients indicates that intact TACR3 function is also required for normal fetal gonadotropin secretion, which stimulates testicular size and descent and penile growth." (PMID 29280744, 2017).
acute kidney injury (1 paper, 2024). Sudden and sustained deterioration of the kidney function characterized by decreased glomerular filtration rate, increased serum creatinine or oliguria. "Furthermore, comparison of transcriptional levels of TACR3 in various renal cell types during acute kidney injury to normal conditions revealed a unique expression profile and implicated the participation of TACR3 in the pathology of kidney injury." (PMID 39427201, 2024).
alcohol dependence (1 paper, 2022). Physical and psychological dependence on alcohol. "Since genetic variation in TACR3 has been associated with alcohol dependence, potential genotypic effects on observed PAE-associated hypomethylation should be studied in the future." (PMID 36581877, 2022).
amenorrhea (1 paper, 2017). The absence of menses in a woman who has achieved reproductive age. "We examined adolescents and young adults with stalled puberty or unexplained amenorrhea for mutations in GNRHR, FGFR1, TAC3, and TACR3 genes." (PMID 29182666, 2017).
leiomyoma (1 paper, 2023). A well-circumscribed benign smooth muscle neoplasm characterized by the presence of spindle cells with cigar-shaped nuclei, interlacing fascicles, and a whorled pattern. "Alterations in the expression profiles of TACR2 and TACR3 genes have been reported for different pathologies, e.g., polycystic ovarian syndrome, leiomyoma, oral carcinoma, or breast cancer." (PMID 36980580, 2023).
mood disorder (1 paper, 2020). A cognitive disorder a disturbance in which the person's mood is hypothesized to be the main underlying feature. "All of these results suggested that Tacr3 might play an important role in terms of TN and its associated mood disorders." (PMID 32264959, 2020).
renal carcinoma (1 paper, 2024). A carcinoma arising from the epithelium of the renal parenchyma or the renal pelvis. "Insights from our multi-omics analysis suggest a significant role of TACR3 not only in renal injury but also in the tumorigenesis and progression of renal carcinomas." (PMID 39427201, 2024). "How does the expression of TACR3 vary across different stages and renal cancer types, and what implications does this have for medical intervention?" (PMID 39427201, 2024). "Here, we commented on these findings by emphasizing the structural and evolutionary significance of TACR3 and provided an in-depth analysis of cell type specific expression of TACR3 in response to renal injury and expressional dynamics during renal carcinoma progression." (PMID 39427201, 2024).
Tinnitus (1 paper, 2025). Tinnitus is an auditory perception that can be described as the experience of sound, in the ear or in the head, in the absence of external acoustic stimulation. "The interactions of TACR1 and TACR3 in the motor system of the thalamus appear to have an inhibitory effect under the conditions of tinnitus, thereby attenuating, inhibiting, or normalizing the influence of tinnitus signals that are perceived in the AuS." (PMID 40565265, 2025).
tumor (11 papers, 2016 to 2026). "GPCRs, including TACR3, have emerged as significant targets for cancer treatment due to their essential roles for regulating abnormal cell growth and facilitating tumor invasion and metastasis." (PMID 39427201, 2024). "The violin plots showed significant differential TACR3 expression between different tumor stages and statistical analysis further confirmed the significance of this variance." (PMID 39427201, 2024). "What kind of role does TACR3 play in the broader context of tumor angiogenesis and metastasis, and how can this be targeted therapeutically?" (PMID 39427201, 2024). "Future research should concentrate on the conserved function and specificity of TACR3, Fezolinetant’s binding sites, and the heterogeneity of TACR3 expression across various tumor types and cell models (see Outstanding questions)." (PMID 39427201, 2024). "The expression level of TACR3 was low in the normal epithelium and was highly elevated in tumor cells." (PMID 36253428, 2022). "At the molecular level, our bioinformatics analysis results suggested that HTR2C, TACR3, MCHR2 and GHSR might be LINC01296 targets through tumor microenvironment and phosphorylation regulation." (PMID 34515611, 2021).
cancer (6 papers, 2018 to 2026). A tumor composed of atypical neoplastic, often pleomorphic cells that invade other tissues. "How does TACR3 interact with other receptors and affect downstream signaling pathways in the context of cancer-associated renal dysfunction?" (PMID 39427201, 2024). "Although TACR3 antagonism show promise for cancer treatment, particularly in tumor-associated disorders, these adverse effects emphasize the importance of ongoing hepatic monitoring and further evaluation to ensure the safe application in conjunction with other means of cancer therapies." (PMID 39427201, 2024). "Recently, the neurokinin 3 receptor (TACR3) has emerged as a crucial factor of renal dysfunction among cancer patients, suggesting its potential as a target for innovative therapeutic intervention." (PMID 39427201, 2024). "In combined treatment with cisplatin, siRNAs against five genes (ADRA2A, F2RL3, NPSR1, NPY and TACR3) enhanced the anti-proliferation efficacy on cancer cells and reduced the self-recovery ability of surviving cells after the removal of the combined treatment." (PMID 36253428, 2022). "Significantly, the study has drawn a parallel illustration with mammals by identifying the neurokinin 3 receptor (TACR3) as the mammalian counterpart of the Drosophila receptor, which highlighted TACR3 as a potential therapeutic target for treating cancer-related renal dysfunction in human patients." (PMID 39427201, 2024). "The expanding role of TACR3 antagonists, including Fezolinetant, is significant, ranging from managing menopausal symptoms to potential applications in hormone-related disorders and cancer therapy." (PMID 39427201, 2024). "Therefore, we can reasonably speculate that TACR3 is a key impact factor of many cancers." (PMID 30485833, 2018).
TACR3 also shares sentences with these, for which no sentence is quoted: Kallmann syndrome (3 papers); polycystic ovary syndrome (3); preeclampsia (3); asthma (2); bladder cancer (2); depression (2); Obesity (2); trigeminal neuralgia (2); Anosmia (1); anxiety disorder (1); Arrhythmia (1); astrocytoma (1); atrial fibrillation (1); chronic obstructive pulmonary disease (1); cognitive deficits (1); colitis (1); colon tumors (1); diabetes (1); gastrointestinal disorders (1); gingival cancer (1); Gonadotropin deficiency (1); infection (1); insulinoma (1); meningoencephalitis (1); neuroblastoma (1); neurodevelopmental disorder (1); neurological disorders (1); Noonan syndrome (1); of puberty (1); Parkinsonism (1).
A further 5 diseases each share a sentence with TACR3 in 1 paper.